TLR2 (toll like receptor 2)
Diseases named in the same sentence as TLR2 in open-access papers (continued):
Sharing a sentence is not in itself a finding about the gene and the disease.
nasal polyps (8 papers, 2005 to 2020). "The overexpression of TLR-2 mRNA is essentially markers of excessive inflammation, which may cause exaggerated signal cascade, triggering uncontrolled cytokine formation, contributing to the formation of nasal polyps." (PMID 33238997, 2020). "Our data highlights the excessive expression of TLR-2 in nasal polyps contributing to the imbalance in Th17/Tregs population in patients." (PMID 33238997, 2020). "The study highlights excessive expression TLR-2 in nasal polyps contributing to the imbalance in Th17/Tregs population in patients of chronic rhinosinusitis." (PMID 33238997, 2020). "The expression of TLR2, 3, and 4 has been shown in nasal epithelial cells derived from nasal polyps, with poly(I:C) inducing the secretion of RANTES, IP-10, IL-8 and GM-CSF." (PMID 26668716, 2015). "At the protein level, TLR2 was found to be expressed in hCBMC and in nasal polyps MC." (PMID 22876248, 2012). "TLR2 at the protein level was found on immature human mast cells as well as on mature mouse mast cells isolated from peritoneal cavity and intestine, and mature nasal polyp human mast cells." (PMID 21765618, 2011). "Martens and colleagues (submitted, 2020) have demonstrated that L. casei AMBR2 could increase epithelial barrier function in primary cell layers derived from CRSwNP (CRS with nasal polyps) patients via upregulation of the same tight junction proteins, presumably through a TLR-2 mediated mechanism." (PMID 33037304, 2020). "Notably, it has been reported that SEB not only enhances Th2 response through interaction with TLR2 signaling but also plays a potential role in IL-5, IL-13, and RANTES production in dispersed nasal polyps following the development of CRSwNP." (PMID 30764556, 2019).
neuroblastoma (8 papers, 2007 to 2025). Neuroblastoma (NB) is the most common solid, extracranial childhood tumor. "Here we demonstrate that activation of macrophages by the TLR2 agonist Pam3CSK4 can also cause neuronal death, and that neuroblastoma cells expressing G93A-SOD1 are more susceptible to the attack of activated immune cells than those expressing wild-type SOD1." (PMID 17997855, 2007). "It would also be advantageous to confirm TLR2-dependent effects in the midbrain model by knocking out TLR2 and/or using TLR2 antagonists as we have previously done using SH-SY5Y neuroblastoma cells." (PMID 39681872, 2024). "In addition, TLR2 knock-out in a human neuroblastoma cell line and the use of a small molecule TLR2 inhibitor (NPT1220-321) in induced pluripotent stem cell-derived neurons from a patient with PD have both demonstrated that αSyn pathology can be attenuated." (PMID 37569837, 2023). "Notably, in models of apoptosis in human neuroblastoma cells and ischemia-reperfusion injury in retina, argon was proven to mediate neuroprotection via inhibiting TLR2 and TLR4." (PMID 31159847, 2019). "After stimulation of human neuroblastoma and macrophage co-cultures with the TLR2 agonist Pam3CSK4 for a period of 72 hours the release of neuron-specific enolase (NSE) was measured in the culture supernatants and expressed as per cent of the NSE release induced by cell lysis." (PMID 17997855, 2007). "Although TLR2 and TLR4 is usually expressed on the cell surface of immune cells, there are a number of reports on intracellular expression of these receptors in various cell types such as coronary artery endothelial cells, intestinal epithelial cells and neuroblastoma cell line." (PMID 24966802, 2014).
Salmonella Infections (8 papers, 2015 to 2025). Infections with bacteria of the genus SALMONELLA. "TLR2 mRNA expression was induced in the Salmonella infection, but previous association with mucinolytic B. boum RP36 prevented statistically significant induction of TLR2 mRNA." (PMID 38003758, 2023). "In the MLN, expression of CD14, TLR2, and MyD88 all increased in response to Salmonella-infection, except in piglets previously innoculated with the probiotic E. coli." (PMID 31847111, 2019). "A network analysis identified an interaction between the Toll-like receptor pathway and Salmonella infection via TLR4 and TLR2, the NOD-like receptor pathway and Salmonella infection via GBP1, and the TNF signaling pathway and Salmonella infection via IRF1." (PMID 40005871, 2025). "TLR2 and TLR4 signaling plays a role in regulating the immunomodulatory functions of FRCs, enabling these cells to orchestrate peritoneal immunity in mouse Salmonella infection." (PMID 38827745, 2024). "Considered to the function of TLR2, TLR4, TLR7, TNF2, IL8, and IL18, it was revealed that the immune defense would been inhibited for REV infection through salmonella infection, NOD-like receptor, Toll-like receptor and MAPK-AP1 pathways." (PMID 29410628, 2018). "Moreover, TLR2, TLR4, TLR7, and IL8 were enriched in Toll-like receptor pathway, IL8 and IL18 were enriched in the NOD-like receptor pathway, and TLR4, IL8, and IL18 were enriched in the salmonella infection pathway." (PMID 29410628, 2018).
acute coronary syndrome (7 papers, 2011 to 2025). Signs and symptoms related to acute ischemia of the myocardium secondary to coronary artery disease. "Recent studies revealed that median TLR2 and -4 expressions on platelets and plaque debris were greater in patients with acute coronary syndrome compared to those with stable angina pectoris." (PMID 29077004, 2017). "Increased activation of TLR2 and -4 was observed also in human circulating monocytes during acute coronary syndrome." (PMID 29077004, 2017). "Increased expression of TLR-2 and TLR-4 was observed in monocytes from patients with angina and acute coronary syndrome." (PMID 25329057, 2014). "Prior studies have demonstrated the increased expression of TLR2 and TLR4 on monocytes from patients with angina and acute coronary syndrome." (PMID 21698167, 2011).
Behcet disease (7 papers, 2008 to 2022). A chronic, relapsing, multisystemic vasculitis characterized by mucocutaneous lesions, as well as articular, vascular, ocular and central nervous system manifestations. "Behcet disease was associated with a higher frequency of the TLR2-rs2289318 A and C allele (p=0.048, p = 0.008) and TLR2-rs3804099 CT genotype (p = 0.005)." (PMID 38983565, 2022). "This association was confirmed in a second state study consisting of 438 Behcet disease patients and 1000 healthy subjects; TLR2-rs2289318 A and C allele (p=0.001, p = 6.89E-06) and TLR2-rs3804099 CT genotype (p = 2.426E-06)." (PMID 38983565, 2022). "TLR4 gene polymorphisms were found to be associated with Behcet’s disease, but not TLR2 Arg753Gln polymorphism." (PMID 27031066, 2016). "In Behcet’s disease, a chronic inflammatory disorder, TLR 2/4 expression negatively correlated with vitamin D3 and importantly, the dose dependent treatment of vitamin D3 decreased inflammation, as also decreased the expression of TLR-2/4." (PMID 26496711, 2015). "Levels of expression of HO-1 mRNA were significantly reduced in PBMCs from patients with active Behçet's disease, whereas those of TLR4, but not TLR2, were increased in PBMCs, regardless of disease activity." (PMID 18234118, 2008).
corneal infection (7 papers, 2009 to 2020). A viral or bacterial infectious process affecting the cornea. "Another study demonstrated reduced inflammatory cell recruitment in Dectin-1 KO mice during a corneal infection model with Aspergillus, whereas cell recruitment was unimpaired in TLR2 KO or TLR4 KO mice; however, fungal killing was impaired in TLR4 KO mice." (PMID 29401615, 2018). "During corneal infections, IL-1β, IL-6, IL-8, and TNFα are important in the initiation of inflammatory signals and both TLR2 and TLR5 mediate microbial clearance and cytokine production during S. aureus and PA keratitis." (PMID 28796783, 2017). "We found that neutrophils comprised >90% cells in corneal ulcers, and that there was elevated expression of TLR2, TLR4, TLR5 and TLR9, the NLRP3 and NLRC4 inflammasomes and the ASC adaptor molecule." (PMID 23750216, 2013). "Glucocorticoids, such as hydrocortisone, can inhibit the expression of TLR2 and TLR4 on HCFs, and thus may increase susceptibility to cornea infections." (PMID 19956406, 2009).
dementia (7 papers, 2017 to 2025). Loss of intellectual abilities interfering with an individual's social and occupational functions. "Increased expression and activation of TLR2 is associated with the progression of neurodegenerative diseases, such as PD and dementia." (PMID 29731715, 2018). "While a similar fold change in TLR2 protein expression has been shown in patients with dementia with Lewy bodies compared to controls, the association with increased neuronal expression has not been previously identified in patients with Lewy bodies." (PMID 27888296, 2017). "IL-1β activates the TLR2/MyD88/NF-κB pathway in Parkinson’s disease, leading to α-synuclein spreading in Parkinson’s disease (PD), multiple-system atrophy (MSA), and dementia with Lewy bodies." (PMID 40801649, 2025).
helminth infection (7 papers, 2008 to 2023). "In summary, ex vivo whole blood analysis of mRNA profiles in children infected with helminths compared to non-infected children living in a rural area in Ghana have shown that chronic helminth infections are associated with a lower expression of TLR2 and SOCS-3." (PMID 18414649, 2008). "In rural Ghana, helminth infection is associated with low TLR2 as well as low SOCS-3 expression, whereas the expression of TLR2 is high in a European rural area." (PMID 18414649, 2008). "Thus, we demonstrate for the first time that NETosis occurs during natural human helminth infection and demonstrate a mechanism of NETosis induction via Wolbachia endobacteria and direct ligation of Wolbachia lipoprotein by neutrophil TLR2/6." (PMID 27752109, 2016). "Malaria infection was associated with higher levels of TLR2 expression (not shown), and adjustment for malaria infection did not change the association between helminth infection and TLR2 expression." (PMID 18414649, 2008). "Increased TLR2 and TLR4 expression in circulating B-cells during helminth infection has already been demonstrated, reflecting systemic exposure to the microbial ligands." (PMID 34784389, 2021). "A similar reduced AAM response was observed in Tlr2–/–mice infected with M. corti and correlated with increased parasite burden suggesting that AAM response controls the helminth infection in brain microenvironment." (PMID 27332553, 2016). "The expression of both TLR2 and TLR4 genes was lower in children with a helminth infection; the effect being more prominent for TLR2." (PMID 18414649, 2008).
intracerebral hemorrhage (7 papers, 2015 to 2022). A cerebrovascular disorder characterized by bleeding into one or both cerebral hemispheres including the basal ganglia and the cerebral cortex. "SsnB is a polyphenolic natural compound that improved intracerebral hemorrhage and endotoxin shock outcomes in mice in a TLR2/TLR4-dependent manner." (PMID 36359764, 2022). "In a mouse model of intracerebral hemorrhage, increased expression of Tlr2 was observed, resulting in a proinflammatory gene profile with activation of Mmp9." (PMID 31083655, 2019). "Toll-like receptor 2 (TLR2) was recently shown to contribute to secondary brain damage after intracerebral hemorrhage (ICH), although the molecular mechanisms of this contribution are elusive." (PMID 28646881, 2017). "For example, during intracerebral hemorrhage, hemoglobin from the hematoma can activate macrophages via Toll like receptor 2 (TLR2)/Toll like receptor 4(TLR4) heterodimer, which can secrete IL-23 to induce γδ T cells to produce IL-17 to aggravate secondary damage." (PMID 33868300, 2021). "In TLR2−/− mice, activation of the matrix metalloproteinase-9 (MMP9) in astrocytes was lower than in wild type (WT) mice, and this reduction resulted in attenuated damage to the BBB in TLR2−/− mice with intracerebral hemorrhage." (PMID 31998072, 2019).
liver cirrhosis (7 papers, 2013 to 2023). "Lipopolysaccharide (LPS) or endotoxin promotes systemic inflammation by activating TLR-2 and TLR-4 dependent pathways and promoting cytokines in large quantities, thereby accelerating the progression of liver cirrhosis." (PMID 34712665, 2021).
lung adenocarcinoma (7 papers, 2013 to 2025). A carcinoma that arises from the lung and is characterized by the presence of malignant glandular epithelial cells. "Toll-like receptors (TLRs), such as Toll-Like Receptor 2 and 4, are pillars of the immune system that have been linked to several forms of malignancy including lung adenocarcinoma." (PMID 36138770, 2022). "This antagonizes TLR2/3-induced progression of lung adenocarcinoma cells." (PMID 41003841, 2025). "Additionally, the progression of lung adenocarcinoma is thought to be influenced by the lncRNA C5orf64/miR-582-5p/NDRG2/TLR2 axis." (PMID 40580075, 2025). "In the present study, we have dissected the role of TLRs in this process by knocking out TLR2, 4, and 9 and analyzing how these deletions affect the promoting effect of COPD-like airway inflammation on K-ras-driven lung adenocarcinoma." (PMID 37283745, 2023). "The results of Western blotting showed that BTG2, TLR2, and IL7R proteins were markedly downregulated in lung adenocarcinoma cell line A549, while CCL20 protein was markedly upregulated." (PMID 35372503, 2022).
lupus nephritis (7 papers, 2012 to 2025). Glomerulonephritis in the context of systemic lupus erythematosus. "It was reported that proteoglycan biglycan induced CXCL13 expression and aggravated lupus nephritis in mice through TLR2/4 on macrophages and dendritic cells." (PMID 32111963, 2020). "The intense and altered expression of TLR2, TLR4, and RAGE in patients with active LN, however, could reflect a role of these receptors in the development and severity of lupus nephritis." (PMID 22892043, 2012).
mycobacterial infection (7 papers, 2011 to 2023). "To study the susceptibility of tlr2 mutants to mycobacterial infection, we analyzed tlr2 mutant zebrafish infected with M. marinum and M. avium." (PMID 35205112, 2022). "The role of TLR signaling in mycobacterial infection has been described in increased susceptibility of TLR2 and MyD88 knockout mice." (PMID 23691111, 2013). "The results show that tlr2 mutant zebrafish are more susceptible to mycobacterial infection." (PMID 35205112, 2022). "Different members of the Toll like receptors (TLR) family, including TLR1, TLR2, TLR4 and TLR6 have been implicated in mycobacterial infection recognition." (PMID 36909724, 2023). "Toll-like receptor 2 (TLR2) is believed to be among the most important Toll-like receptors for defense against mycobacterial infection." (PMID 35205112, 2022). "Cell transplantation techniques can be applied to investigate the non-intrinsic and intrinsic functions of myeloid cells in the tlr2 zebrafish mutant after wounding and mycobacterial infection." (PMID 35205112, 2022). "Compared with TLR4, the function of TLR2 in mycobacterial infection is more complex, because TLR2 can recognize a large number of components on a mycobacterial membrane." (PMID 35205112, 2022). "TLR2 is not only investigated as a promising therapeutic target for mycobacterial infectious diseases, but also for other diseases." (PMID 35205112, 2022). "Tlr2 is conservatively involved in most aspects of the defense against both mycobacterial infections." (PMID 36741407, 2022). "In conclusion, the results show that tlr2 differentially regulates the macrophages and neutrophils dynamic behavior after different mycobacterial infections." (PMID 36741407, 2022). "More functions of TLR2 in innate immune responses to mycobacterial infection, will be discussed in detail below." (PMID 35205112, 2022). "There is consensus that neutrophils are activated upon mycobacterial infection via TLR2-mediated recognition of LAM on the surface of bacteria." (PMID 35205112, 2022). "In a pathway analysis in a zebrafish larval mycobacterial infection model, the expression of the Tlr8 pathway connected to vitamin D signaling was strongly affected in a tlr2 mutant, which implicates a link between Tlr2 and Tlr8 signaling." (PMID 35205112, 2022). "Mice are widely used as animal models to study the function of TLR2 in resistance to mycobacterial infection." (PMID 35205112, 2022). "In this scenario, TLR2 activation in macrophages appears to be critical for mycobacteria recognition as well as being classically recognized as a principal inducer of signals in mycobacterial infection." (PMID 36909724, 2023). "In addition, TLR2 indirectly cooperates with the other TLRs to function in defense against mycobacterial infection." (PMID 35205112, 2022). "To further explore the role of tlr2 in the control mycobacterial infection, we investigated whether tlr2 is also involved in the immune response to M. avium infection." (PMID 36741407, 2022). "However, the reports on the function of TLR2 in the regulation of the recruitment of neutrophils during mycobacterial infection are contradictory." (PMID 35205112, 2022). "Therefore, the other animal models require to be utilized to further study the TLR2 function in mycobacterial infection." (PMID 35205112, 2022). "We hypothesized that tlr2 could also be involved in the regulation of migratory behavior of macrophages and neutrophils to the sites of mycobacterial infection." (PMID 36741407, 2022). "The protective effect of TLR2 signalling in mycobacterial infections was commonly proposed." (PMID 21629653, 2011). "Noteworthy, beyond TLR2 and CD36, blockade of CD14 and CD11b/CD18 also inhibited BCG-induced LDs biogenesis and the synthesis of lipid mediators, suggesting that in addition to CD36 other TLR2 co-receptors may regulate mycobacterial infection-triggered alterations in host lipid metabolism." (PMID 36909724, 2023).
mycobacterial infection (continued). "Activation of multiple TLRs, including TLR2, TLR4, and TLR9, as well as TLR6 and TLR1 when dimerized with TLR2, contributes to an efficient innate response against mycobacterial infection, resulting in inflammatory responses with cytokine production." (PMID 22851964, 2012). "Except for macrophages, the activation of other hematopoietic and non-hematopoietic cells via TLR2 is also required for host resistance to mycobacterial infection." (PMID 35205112, 2022). "It indicates that TLR2 and the other TLRs compensate for the lack of TLR4 function in mycobacterial infection." (PMID 35205112, 2022).